MUC1 (mucin 1, cell surface associated)
Diseases named in the same sentence as MUC1 in open-access papers (continued):
Sharing a sentence is not in itself a finding about the gene and the disease.
breast carcinoma (continued). "MUC1 CAR T with a cytokine switch receptor of IL4 receptor extracellular domain fused to an IL7 intracellular signaling domain can proliferate and suppress tumor growth in mice breast cancer model." (PMID 33381115, 2020). "Studies on MUC1 in African breast cancer samples are virtually nonexistent, as only a handful has been done." (PMID 32377198, 2020). "Similarly, the MUC1 protein can also be targeted using aptamers, increasing the ability of MSNs to inhibit the proliferation of MDA-MB-231 and MCF-7 breast cancer cells." (PMID 32397449, 2020). "In a tumour setting, aberrant glycosylation of MUC1, seen in 90% of breast cancers, exposes epitopes that would not normally be accessible for recognition in normal tissue." (PMID 32645977, 2020). "Previous studies found mucin 1 (MUC1), a transmembrane protein widely expressed in almost all glandular epithelial cells, was a protein that played an important role in the survival, proliferation, and migration of human mammary tumors." (PMID 33375426, 2020). "In particular, human clinical studies of MUC1 conjugated to the carrier mannan has been in phase I, II, III trials, and in early stage breast cancer patients these conjugates show protection against recurrence up to 18 years post-vaccination clinical follow-up." (PMID 31430935, 2019). "As negative control served murine breast cancer cells that did not express human MUC1 after isolation from PyMT (Tg(MMTVPyMT)634Mul mice." (PMID 31588183, 2019). "Finally, MUC1 can also promote EGFR-dependent cell motility and acinar branching of breast cancer cells through the upregulation of c-Met." (PMID 29464085, 2018). "Taken together, our study demonstrates that MUC1-CD plays an important role in regulating microenvironment of PMI and promoting postpartum mammary tumorigenicity, providing novel prevention and treatment strategies against postpartum breast cancer." (PMID 29423058, 2018). "Normal luminal epithelium and luminal breast cancer have been successfully characterized by expression of keratin K8, K19 and MUC1 and lack of expression of keratin K14 and p63." (PMID 28076334, 2017). "Furthermore, MUC1 can interact and contribute to the activation of PI3K/AKT, ERK, and receptor tyrosine kinases (RTKs) to support the growth of breast cancer cells." (PMID 28464016, 2017). "Unlike RAD50, MUC1 has not been classified as a driver gene in breast cancer and was therefore not included in further analysis." (PMID 28241424, 2017). "Mucin 1 (MUC1), a transmembrane glycoprotein, as a critical downstream effector that mediates IGF-1-induced EMT in a PI3K/Akt signaling pathway-dependent manner in breast cancer." (PMID 28137302, 2017). "Notably, among the several members of the mucin family, MUC1, MUC2, MUC3, MUC4, MUC5AC, and MUC6 are expressed in breast cancer." (PMID 28464016, 2017). "By contrast, non-neoplastic breast epithelium from patients with breast cancer showed clear glandular architecture with weak staining with MUC-1 and syndecan-1 antibodies." (PMID 28399903, 2017). "MUC1-ARF expression, as shown here, is seen only in a select sub-group (~40%) of those breast tumors that express MUC1-TM, and thus may designate a breast cancer subtype with a specific prognostic outcome for the following reasons." (PMID 27768738, 2016). "Mucin-1 (MUC1, CD227), more widely known as CA15-3, is an abundantly expressed epithelial cell surface antigen and has evolved to be the most predictive serum tumour marker in breast cancer." (PMID 25986064, 2015). "The significance of MUC1 as a relevant therapeutic target is highlighted by its atypical expression in > 64% of carcinomas diagnosed annually, and in over 90% of breast carcinomas irrespective of hormone or growth factor receptor status." (PMID 26147830, 2015). "Furthermore, miR-125b was found to suppress the oncoproteins MUC1, ERBB2, and ERBB3, inhibiting the growth of breast cancer cells." (PMID 26693202, 2015).
breast carcinoma (continued). "Nevertheless, concordant blockage of MUC1 and ER has failed to be effective in a randomized phase II trial performed with locally advanced, metastasized breast cancer." (PMID 25986064, 2015). "Despite the lack of specificity, MUC1-directed assays in combination with other serum biomarkers are routinely used in the complex diagnosis of breast cancer." (PMID 26509158, 2015). "There are known research works about combined therapy with monoclonal antibody C595 and docetaxel in several ovarian cell cancers, but there are no data about combined therapy platinum compounds with anti-MUC1 in breast cancer cell lines." (PMID 24639126, 2014). "A novel dinuclear platinum(II) complex (Pt12) used with anti-MUC1 was compared to its parent drug and cisplatin with anti-MUC1 in respect to cytotoxicity, DNA, and collagen biosynthesis in MDA-MB-231 and MCF-7 human breast cancer cells." (PMID 24639126, 2014). "Mucin 1 (MUC1) is a type I transmembrane glycoprotein that is expressed on apical membranes in a variety of normal tissues, but aberrantly is overexpressed in various cancer cells especially in breast cancer cells." (PMID 24639126, 2014). "It was reported that CD44+ progenitor-like cells of normal mammary epithelium were globally hypomethylated compared to luminal epithelial (CD24+ and MUC1+) and myoepithelial (CD10+) cells and cell type-specific methylation patterns were conserved in breast cancer." (PMID 24971511, 2014). "Reports have shown nucleolar localization of MUC1 in human breast carcinomas but not in normal mammary ductal epithelium." (PMID 25261375, 2014). "There are known research works on the use of anti-MUC1 antibody with docetaxel in ovarian cancer, but there are no data about combined therapy platinum compounds with anti-MUC1 in breast cancer." (PMID 24639126, 2014). "We determined whether Pt12, cisplatin, Pt12 with anti-MUC1, and cisplatin with anti-MUC1 induced DNA fragmentation in MCF-7 breast cancer cells." (PMID 24639126, 2014). "Tumour-associated changes such as the Tn antigen and other changes in O-glycosylation have been found to be immunogenic and present on a variety of proteins, e.g. CD43 in T-cell leukaemia cells, MUC-1 in colon cancer, CD44 in breast carcinoma and nucleolin in melanoma." (PMID 23637900, 2013). "In the present study, we did not observe differences in MUC1 expression between multicentric/multifocal and unifocal breast cancer (p = 0.183)." (PMID 23890049, 2013). "We clearly show that the stability of EGFR protein is reduced in MUC1 knockdown cells, suggesting that MUC1 potentiates BPDE-induced EGFR activation through stabilization of the latter, similarly as in ligand-induced EGFR activation in breast cancer cells." (PMID 22457794, 2012). "In repeated experiments, we failed to observe colony formation in lung tissue from the control MUC1.Tg mice, which do not develop breast carcinoma." (PMID 22277639, 2012). "Additionally, a low molecular weight MUC1 cleavage product, MUC1*, that remains membrane bound has recently been shown to be a determinant of trastuzumab resistance in HER2+ breast cancer and functions as a growth factor receptor." (PMID 23285151, 2012). "By contrast, we detected no mammary tumor formation in WT mice injected with lung cells from MUC1.Tg control mice." (PMID 22277639, 2012). "We have been investigating the mechanism of cell migration in the Luminal B breast cancer cell lines MCF7 and T47D, and were the first to demonstrate that MUC1 mediates heterotypic cell-cell adhesion by binding ICAM-1, which is expressed on peritumoral stromal and endothelial cells." (PMID 21798038, 2011). "Complement-dependent cytotoxicity (CDC) against a breast cancer cell line was seen in seven of nine patients, but possibly not due to MUC1 abs, as these do not mediate CDC." (PMID 24212946, 2011).
breast carcinoma (continued). "MUC1 (also known as DF3, CA15-3, or episialin) is expressed apically on normal breast epithelia, but often loses this polarization and becomes underglycosylated in breast cancer." (PMID 21798038, 2011). "Indeed, the serum assay widely used for monitoring disease progression in breast cancer (CA15.3), detects a glycoprotein (MUC1), but elevated levels of the antigen cannot be detected in early stage patients." (PMID 21385452, 2011). "Furthermore, a humanized anti-MUC1 MAb (huHMFG-1) induced strong ADCC to breast cancer cells and is currently being used in a clinical trial for breast cancer." (PMID 21931707, 2011). "We were the first to report binding between MUC1 and Intercellular adhesion molecule-1 (ICAM-1), which is expressed on stromal and endothelial cells throughout the migratory tract of a metastasizing breast cancer cell." (PMID 21798038, 2011). "Ligation of MUC1 and ICAM-1 may represent a mechanism for movement of breast cancer cells through stromal and endothelial tissues." (PMID 21798038, 2011). "Reports from a phase III trial of a breast cancer vaccine, Theratope, indicated that aromatase inhibitors may increase ADCC, adding to the rationale for combining anti-MUC1 antibodies with this approach to estrogen reduction." (PMID 19811637, 2009). "Our results also show that in MUC-1-negative CAR-positive breast cancer tumors, the NIS gene also can be expressed, because it is under the control of the ubiquitous RSV promoter." (PMID 19635153, 2009). "Conversely, the MUC-1-negative breast cancer cell line MDA-MB-231 was refractory to the viral cytopathic effect and did not support viral replication." (PMID 19635153, 2009). "Bands corresponding to MUC1 could be recognised by TKH2 in E3STn and the epithelial breast cancer cell lines MCF7-STn and T47-D-STn." (PMID 19436292, 2009). "Of nine breast cancer specimens tested, only one was a MUC1-negative cancer, which roughly corresponds to published reports that approximately 90% of all breast cancers are MUC1-positive cancers." (PMID 18446242, 2008). "We panned them, along with a peripheral blood lymphocyte (PBL)-derived library from a single breast tumor patient, on living MCF7 breast carcinoma cells, as well as on three purified tumor surface antigens, i.e., CEA (carcinoembryonic antigen), MUC1 (epithelial mucin) and ED-B domain of fibronectin." (PMID 17945015, 2007). "TMAs have also been utilised with MUC1 and MUC3 expression in breast cancer." (PMID 17349047, 2007). "We showed for the first time that estrogen differentially regulates expression of the MUC1 isoform specific mRNAs in human breast cancer cells: it activates expression of the MUC1/SEC isoform but does not affect expression of the MUC1/TM mRNA." (PMID 17083744, 2006). "Overexpression of MUC1 along with MUC2 and MUC3 has been detected in breast cancer." (PMID 16595007, 2006). "To determine whether GATA3 protein was actively bound to the predicted consensus MUC1 promoter sequence (at -2398/-2393 from the transcriptional start site (TSS)) in vivo and in vitro, we performed ChIP and gel shift analyses in breast cancer cells." (PMID 17078870, 2006). "MUC1 and MUC3 were detected in the majority of breast cancer cases." (PMID 16595007, 2006). "For example, although we found that DCs loaded with whole tumor cells are not efficient in cross-presenting MUC-1, a recent study demonstrated that loading DCs with breast cancer cell lysates permits more efficient priming of MUC-1 specific CD8+ T cells." (PMID 17129372, 2006). "Two human breast cancer cell lines, MDA-MB-468 and BT-20, were transiently transfected with a pool of four siRNA oligonucleotides directed against the MUC1 mRNA (468.siMUC1 and BT.siMUC1), or a control oligonucleotide directed against luciferase (468.siLuc and BT.siLuc)." (PMID 16846534, 2006).
breast carcinoma (continued). "Variable degrees of expression of MUC1 and CD44 (exons 8-11) were detected in normal peripheral blood, rendering these genes non-specific for epithelial cells and therefore unsuitable for use as markers to detect breast carcinoma cells." (PMID 9579823, 1998). "The limitations of this study include the lack of data on changes in the oral microbiome in breast cancer patients, which may also have influenced the reduction in MUC1 levels." (PMID 39456554, 2024). "Stimuvax (i.e., MUC1-specific), Tecemotide (i.e., MUC1-specific), and sHER2+AS15 are notable examples of liposome-based cancer nanovaccines that have progressed through phase-II/III clinical trials to treat melanoma and NSCLC, breast cancer, and PDAC, respectively." (PMID 35154473, 2022). "Interestingly, these mammary tumors exhibited low expression levels of PRLR as well as other luminal and epithelial differentiation markers such as (Elf5, Muc1), claudins, and cell adhesion markers (Cdh1, Ocln), while showing elevated levels of EMT and BCSC markers." (PMID 33446633, 2021). "Breast cancer tissues have remarkably high MUC1 expression compared to normal tissues." (PMID 33194611, 2020). "The positivity of 16A mAb staining in breast cancer (90%) is greater than that of SAR566658,30, 31, 32 which binds to a sialylated unknown MUC1 sequence in bladder, breast, ovary, pancreatic, head, and neck cancers with positivity rates of 59%, 29%–35%, 70%, 59%, and 17%, respectively." (PMID 33084221, 2020). "And Snail can also inhibit the expression of other epithelial genes such as Claudin1 and Muc1 and promote the expression of other mesenchymal genes such as fibronectin, MMP9 and vimentin, which activates EMT and is related to tumor metastasis, recurrence and poor prognosis in breast cancer." (PMID 32028981, 2020). "In summary, our data provide in vivo evidence for the function of MUC1-CD in the PMI and postpartum breast cancer, suggests that MUC1-CD-targeted therapies toward the window of PMI of corresponding subtypes could be preventive for postpartum breast cancers." (PMID 29423058, 2018). "We have recently synthesized aptamer-functionalized silver nanoclusters (AgNCs) based on a MUC1 aptamer for imaging of MCF-7 breast cancer cells, which could efficiently differentiate MCF-7 cells from more aggressive MDA-MB-231 breast cancer cells and A549 human lung cancer cells." (PMID 29132385, 2017). "A high red fluorescent signal of free DOX molecules could be observed upon binding of the negatively charged complex to the MUC1 positive breast cancer cells but not with MUC1 negative cells." (PMID 29144411, 2017). "Furthermore, Pam3Cys-containing vaccines led to a reduction of mouse mammary tumor burden and induced CTLs capable of killing MUC1-overexpressing cell lines, neither of which was observed after treatment with CpG-containing vaccines." (PMID 26557640, 2015). "Interestingly, in a small clinical study in early stage breast cancer patients immunized with mannan-MUC1, the vaccine induced both humoral and T-cell responses to non-glycosylated MUC1 and eliminated recurrence of disease." (PMID 23189185, 2012). "MUC1 positive human breast cancer cell lines MCF-7 and T47D and HEK 293T cells transfected with MUC1-CFP or the MUC1 splice variant lacking the tandem repeat domain MUCY-YFP-Fv were lysed with or without prior treatment with the membrane permeable crosslinker DSS." (PMID 21798038, 2011). "Our findings also support that, in breast cancer, Lewis y may be part of circulating MUC1 glycoform structure and that Lewis y/CIC do not correlate with Lewis y expression." (PMID 19715603, 2009). "Virus specificity was demonstrated by using the MUC-1-negative breast cancer cell line MDA-MB-231." (PMID 19635153, 2009). "Moreover, these sera reacted with only with primary human breast cancers that expressed MUC1 and STn (data not shown)." (PMID 19436292, 2009).
breast carcinoma (continued). "In solid tumors like breast cancer, preclinical models suggest that dual-target CAR-Ts may mitigate off-tumor cytotoxicity through selective targeting of co-expressed antigens, such as HER2 and MUC1, limiting systemic cytokine release and improving safety margins." (PMID 41348261, 2025). "In addition, the cytolytic function of CAR MUC1 T cells was evaluated in primary breast cancer, in which both CAR MUC1 constructs demonstrated a specific antitumor activity and increased interferon gamma and IL-2 secretion after coculturing with MUC1+ primary cells." (PMID 36457849, 2022). "In addition, MUC1 and IGF1R co-expressed with CTD-2566J3.1 had AUC > 0.6 and were found significantly over-expressed in patients without response to therapy, indicating that down-regulation of these mRNAs can modestly discriminate PCR in patients with luminal B breast cancer." (PMID 36359853, 2022). "Nevertheless, a study involving a large patient cohort and healthy controls demonstrated that the levels of anti‐MUC1 autoantibodies in patient sera are similar to those of healthy controls, suggesting that autoimmunity to MUC1 in breast cancer may not be enhanced." (PMID 33506656, 2021). "MUC1 may contribute to metastasis, as it was demonstrated in vitro that the MUC1 protein can bind to intercellular adhesion molecule-1 (ICAM-1), which facilitates adhesion of breast cancer cells to endothelial cells, leading to adhesion and subsequent migration through the vessel wall." (PMID 24810688, 2014). "Interestingly, MUC1 serum levels in breast cancer patients were not concordant with the levels observed in tumor tissues by immunohistochemistry, so the increased serum MUC1 expression may correspond to a specific isoform expressed by cancer cells." (PMID 16117833, 2005). "Six breast cancer patients immunized with this conjugate plus the immunological adjuvant QS-21 have all produced high titre (by ELISA) IgG and IgM antibodies against the 30 aa MUC1 peptide, but these sera reacted moderately, or not at all, with MUC1-positive tumour cells." (PMID 10206297, 1999). "Immunohistochemical (IHC) staining analysis revealed a negative correlation between MUC1 and ATAD3A not only in all breast cancer patients but also in four subtypes of breast cancer patients—luminal A, luminal B, HER2 and TNBC." (PMID 36289190, 2022). "Along the same line, the MUC1-expressing breast cancer cell lines MCF7 and T-47D also showed strong staining with anti-MUC1 Tn antibodies, while the MUC1 Tn-negative breast cancer cell line SK-BR-3 was only recognized by pan-MUC1 antibodies." (PMID 34070311, 2021). "As a control, MCF-7 luminal breast cancer cells showed negative staining of basal markers (P63, CK14, Vim, CK5, CK17, N-cad) but positive staining of luminal markers CK18, CK8, E-cad, CK7, Muc1, ER, and PR." (PMID 26147507, 2015). "In a breast cancer mouse model, mucin 1 (MUC1 for human and Muc1 for nonhuman species) facilitated TGFα-induced EGFR activation and breast cancer development." (PMID 22457794, 2012). "Mucin 1 (MUC1), a membrane bound glycosylated phosphoprotein predominantly expressed by epithelial cells, is suggested to be a marker for detection of breast-cancer cells not expressing EpCAM." (PMID 21816090, 2011). "Using these gene markers [mam, CEA, CK19, PIP, muc1, PSE, Erb (BM only) and EpCAM (PBL only)] we analyzed 215 PBL samples and 177 BM samples from patients with T1-T3 primary breast cancer without clinical evidence of metastatic disease." (PMID 18289390, 2008). "For instance, estrogen activated expression of MUC1/SEC, but not MUC1/TM isoform in human breast cancer epithelial cells." (PMID 17083744, 2006). "It is also apparently a set of breast carcinomas in which there was no direct correlation between levels of GATA3 and MUC1 expression." (PMID 17078870, 2006).